PDE7A (phosphodiesterase 7A)
Description:
Hydrolyzes the second messenger cAMP, which is a key regulator of many important physiological processes. May have a role in muscle signal transduction.
Synonyms: HCP1; PDE7
Tractability: Small molecule: an approved drug acts on it; a structure with a bound ligand is known; a high-quality ligand is known; it has a high-quality binding pocket; it belongs to a druggable protein family. PROTAC: ubiquitination databases record sites on it; a small molecule that binds it is known.
Target class: Enzyme; Phosphodiesterase 7A; Phosphodiesterase 7; Phosphodiesterase
Gene: Protein-coding gene on chromosome 8 (65,714,334 to 65,842,529, reverse strand). Ensembl gene ENSG00000205268.
Subcellular location: Cytoplasm, cytosol (Isoform PDE7A1); Cytoplasm (Isoform PDE7A2)
Pathways (Reactome):
Signal Transduction: G alpha (s) signalling events
Gene Ontology:
Molecular function: 3',5'-cyclic-AMP phosphodiesterase activity; 3',5'-cyclic-GMP phosphodiesterase activity; 3',5'-cyclic-nucleotide phosphodiesterase activity; cyclic-nucleotide phosphodiesterase activity; phosphoric diester hydrolase activity
Biological process: negative regulation of cAMP/PKA signal transduction; cAMP catabolic process; signal transduction
Cellular component: cytoplasm; cytosol
Genetic constraint (gnomAD): Loss-of-function variants: 10 observed, 13.7 expected, observed/expected ratio (o/e) 0.73, 90% interval 0.45 to 1.24. The upper end of that interval is the gene's LOEUF score, 1.24, which puts it in group 5 of 6, group 1 being the genes least tolerant of losing a copy. Missense variants: 193 observed, 192.96 expected, observed/expected ratio (o/e) 1, 90% interval 0.89 to 1.13. Synonymous variants: 80 observed, 74.7 expected, observed/expected ratio (o/e) 1.07, 90% interval 0.89 to 1.29.
Homologues: Orthologues: chimpanzee PDE7A (100% identical), guinea pig PDE7A (98% identical), pig PDE7A (98% identical), dog PDE7A (98% identical), rabbit PDE7A (97% identical), mouse Pde7a (94% identical), macaque PDE7A (91% identical), rat Pde7a (89% identical), tropical clawed frog pde7a (84% identical), zebrafish pde7a (77% identical), Caenorhabditis elegans pde-6 (22% identical), Drosophila melanogaster Pde8 (22% identical), and 2 more. Paralogues in human: PDE7B (53% identical), PDE4A (29% identical), PDE4D (29% identical), PDE4B (29% identical), PDE4C (28% identical), PDE3A (27% identical), PDE3B (27% identical), PDE1C (26% identical), PDE8B (26% identical), PDE1A (25% identical), PDE1B (25% identical), PDE8A (25% identical), and 8 more.
Diseases named in the same sentence as PDE7A in open-access papers:
PDE7A is named in the same sentence as 58 diseases in open-access papers, as found by Europe PMC text mining. Sharing a sentence is not in itself a finding about the gene and the disease. The quoted sentences say what the papers report.
asthma (6 papers, 2019 to 2025). "Using bioinformatics analysis, the target genes interacting with miRNAs related to the airway inflammatory response, airway remodeling and other pathological change processes in asthma were screened as ABL2, MMP16 and PDE7A." (PMID 36611831, 2022). "In addition to these miRNAs that could target and regulate multiple key targets, hsa-miR-146a-5p, as one of the predicted miRNAs, was upregulated in asthmatic patients to inhibit the expression level of PDE7A, which might be involved in mediating the pathogenesis of asthma." (PMID 35586697, 2022).
breast carcinoma (4 papers, 2017 to 2025). "We also observed that higher PDE7A mRNA levels were more strongly associated with TNBC than with other breast cancer subtypes." (PMID 40961924, 2025). "Furthermore, PDE7A overexpression in ductal breast carcinoma samples was associated with an increased incidence of disease recurrence and reduced overall survival in breast cancer patients." (PMID 40961924, 2025). "We found that 7 out of 10 transcription factors displayed significant correlation with the mRNA expression of PDE7A in breast cancer samples." (PMID 40961924, 2025). "Next, we asked if the expression of these transcription factors also significantly correlated (either negatively or positively) with the expression of PDE7A mRNA in breast cancer samples." (PMID 40961924, 2025).
Hepatitis (4 papers, 2020 to 2022). Inflammation of the liver. "In another study, a PDE inhibitor with a strong activity against PDE7A (IC50 = 9 nM) has been investigated in the ConA-induced hepatitis model and it decreased ALT activity and TNF-α levels." (PMID 31899535, 2020). "Taken together, these results suggest that simultaneous inhibition of both PDE7A and PDE4B induced anti-inflammatory effects in ConA-induced hepatitis by inhibiting the production of pro-inflammatory mediators." (PMID 33919375, 2021). "The results presented in this paper indicate that due to the balanced anti-inflammatory properties, resulting mainly from PDE7A and, to a lesser extent, PDE4B inhibition, GRMS-55 exhibited high hepatoprotective activity in mice with ConA-induced hepatitis." (PMID 33919375, 2021). "Thus, it can be concluded that the observed effects of PDE inhibitors in ConA-induced hepatitis arise both from the inhibition of PDE4B and PDE7A." (PMID 31899535, 2020).
endometrial cancer (3 papers, 2017 to 2022). Primary or metastatic malignant neoplasm involving the endometrium (mucous membrane that lines the endometrial cavity). "Inhibition of PDE7A expression inhibits cancer cell proliferation, migration and invasion in endometrial cancer, while overexpression of PDE7A has the opposite effects." (PMID 36685103, 2022). "MiR-1 has approximately 1000 predicted targets in different cell types, with only phosphodiesterase 7A (PDE7A) experimentally confirmed in endometrial cancer cells." (PMID 28186993, 2017).
colon cancer (2 papers, 2023 to 2025). "miR-23b inhibits cell migration and invasion through targeting phosphodiesterase 7A (PDE7A) in colon cancer cells." (PMID 36609391, 2023). "Lowering PDE7A expression with miR-23b or silencing PDE7A could also reduce the migration and invasion abilities of colon cancer cells (SW620 and SW480 cells)." (PMID 41179677, 2025).
endotoxemia (2 papers, 2020 to 2022). "The inhibition of PDE7A seems to display an additional anti-inflammatory effect, as a strong inhibitor of PDE7A – GRMS-55 demonstrated ~5.5 and ~4.0 times lower IC50 values in LPS-induced endotoxemia and CIA, respectively, than (±)-LSF, which is only a ~2.0 times weaker PDE4B inhibitor than GRMS-55." (PMID 31899535, 2020).
glioma (2 papers, 2024 to 2025). A benign or malignant brain and spinal cord tumor that arises from glial cells (astrocytes, oligodendrocytes, ependymal cells). "MiR-218-phosphodiesterase 7A (PDE7A) signaling axis is another mediator linking hyperactivation of HOTAIR and glioma pathogeneses." (PMID 38366205, 2024).
alcohol use disorder (1 paper, 2024). "Therefore, the results not only advance our understanding of the role of PDE7A in the responsive effects to EtOH but also underscore the potential of targeting PDE7A as a therapeutic approach for managing alcohol abuse and addiction." (PMID 39099166, 2024). "Inhibition or knockdown of PDE7A attenuates EtOH responsivenessand consumption exclusively in female mice, which is associated with alterations in the cAMP-PKA/Epac2 signaling pathways, thereby highlighting its potential as a novel therapeutic target for alcohol use disorder." (PMID 39099166, 2024).
attention deficit-hyperactivity disorder (1 paper, 2023). A disorder characterized by a marked pattern of inattention and/or hyperactivity-impulsivity that is inconsistent with developmental level and clearly interferes with functioning in at least two settings (e.g. at home and at school). "Similarly, PDE7A was associated with higher odds of attention-deficit/hyperactivity disorder (ADHD) (OR = 1.0861, PIVW = 0.0038)." (PMID 37605207, 2023).
ductal breast carcinoma (1 paper, 2025). "To identify such cancer-specific liabilities, we analyzed patient-derived ductal breast carcinoma samples for the expression of PDEs and identified significant overexpression of PDE7A mRNA in patient-derived ductal breast carcinoma samples compared to normal breast tissues." (PMID 40961924, 2025).
liver steatosis (1 paper, 2021). "Conversely, genes associated positively with serum ferritin (PDE7A) and also with liver steatosis increased significantly after iron exposure." (PMID 33962692, 2021).
lymphoma (1 paper, 2019). A malignant (clonal) proliferation of B- lymphocytes or T- lymphocytes which involves the lymph nodes, bone marrow and/or extranodal sites. "And then it has been suggested that cAMP can inhibit the growth of various types of lymphoma (especially CLL), while PDE7 inhibitors (nonselective for PDE7A and PDE7B) can kill CLL cells by increasing cAMP concentration, which may be a useful treatment for such diseases." (PMID 31740742, 2019).
ovarian carcinoma (1 paper, 2025). A malignant neoplasm originating from the surface ovarian epithelium. "Here, we investigated phosphodiesterase 7A (PDE7A) as a potential target in ovarian cancer treatment." (PMID 40535773, 2025). "Selecting suitable cell line models can maximize the relevance of experiments, as identifying cell lines with alterations in PDE7A expression may provide insights into the clinical aspects of ovarian cancer." (PMID 40535773, 2025).
steatosis (1 paper, 2016). Increased lipid within the cytoplasm of cells. "Alteration in CCR7, IMPDH2, IL6ST, MYC, LPIN1, PDE7A and RORA was significantly associated with hepatotoxicity including liver damage, -hyperplasia, -inflammation, -steatosis, -fibrosis, -necrosis and -proliferation." (PMID 26907258, 2016).
tumor (9 papers, 2017 to 2025). "DHODH suppression attenuates TNBC tumor growth, mirroring the effects of PDE7A inhibition, and ectopic DHODH expression rescues PDE7A-inhibition-induced tumor suppression." (PMID 40961924, 2025). "Inhibition of PDE7A attenuates de novo pyrimidine biosynthesis by repressing DHODH expression, causing suppression of TNBC tumor growth and metastasis." (PMID 40961924, 2025). "In a mouse xenograft model also, ectopic expression of DHODH in PDE7A-KO TNBC cells rescued their tumor growth." (PMID 40961924, 2025). "Experiments in vivo need to be conducted to demonstrate the effects of PDE7A inhibition on tumor progression and to evaluate the safety of the combination treatment with PTX." (PMID 40535773, 2025). "To further strengthen these findings, we genetically knocked down the expression of PDE7A using shRNA and measured the impact on tumor cell growth and metastatic attributes." (PMID 40961924, 2025). "We first tested the impact of pharmacological inhibition of PDE7A on TNBC tumor and metastatic characteristics using cell culture-based assays." (PMID 40961924, 2025). "Collectively, these results demonstrate that PDE7A inhibition by BRL-50481 potently suppresses TNBC tumor growth in both TNBC cell line xenograft- and PDX xenograft-based mouse models." (PMID 40961924, 2025). "Similarly, we tested the combination of 5-fluorouracil (5-FU) and BRL-50481 based on the previous studies in which DHODH inhibitor and 5-FU have shown synergistic effects in tumor suppression and the fact that PDE7A inhibition can suppress DHODH expression." (PMID 40961924, 2025). "Furthermore, PDE7A inhibition blocked TNBC tumor growth and metastasis, which underpins its role as an important driver of TNBC." (PMID 40961924, 2025). "Next, we assessed whether PDE7A inhibition could suppress tumor growth in vivo using complementary mouse models of TNBC tumor growth." (PMID 40961924, 2025). "Next, we examined whether DHODH inhibition exerts similar tumor-suppressive effects on TNBC cells as those observed in response to PDE7A inhibition." (PMID 40961924, 2025). "We found that PDE7A inhibitor, both alone and in combination with a DHODH inhibitor, suppressed TNBC tumor growth and metastasis." (PMID 40961924, 2025). "Several of the understudied genes are directly involved in critical metabolic pathways of tumor etiology, including glucose metabolism (SORD), lipid biosynthesis (FAR1), cAMP signaling pathway (PDE7A, ADCY6), and glutamate anaplerosis (ABAT, GLUD1)." (PMID 31231467, 2019). "Pharmacological co-targeting of PDE7A and DHODH potently inhibits TNBC tumor growth and metastasis." (PMID 40961924, 2025). "Similarly, in triple-negative breast cancer cell lines MDA-MB231 and Hs578T, PDE7A has been shown to promote tumor growth." (PMID 40535773, 2025). "PDE7A-KO TNBC cells without or with DHODH overexpression were subcutaneously injected into the flanks of female NSG mice, and tumor growth was measured." (PMID 40961924, 2025).
cancer (7 papers, 2017 to 2025). A tumor composed of atypical neoplastic, often pleomorphic cells that invade other tissues. "Additionally, overexpression of PDE7A in endometrial cancer (EC) cells facilitates cancer cell migration and invasion through the suppression of the miR-1/133a microRNA cluster." (PMID 41179677, 2025). "Among these, LCOR and PDE7A have been shown to play roles in other types of cancer." (PMID 36685103, 2022). "Thus, dysregulated miRNA-target gene pairs involved in these genes like miR-21/GNE, miR-369/TRIM2, and miR-203a/PDE7A might promote the migration of cancer cells." (PMID 30627543, 2018). "The rationale for combining both PDE7A and DHODH inhibitors is supported by previous studies in which targeting multiple nodes of the same cancer driver pathway has been shown to achieve better clinical outcomes." (PMID 40961924, 2025).
hematological disease (1 paper, 2022). "In addition, genes associated with hematological disease (e.g., PDE7A, LMAN1, F13A1, OLR1) and mitochondrial biogenesis and redox (e.g., NOS3, ALDH5A1, PRXL2A, SLC25A13, CPT2) were also significantly altered in BPD patients." (PMID 35484630, 2022).
inflammation (1 paper, 2019). Aberrant reaction of the microcirculation characterized by movement of fluid and leukocytes from the blood into extravascular tissues. "However, a study showed no involvement of PDE7A and PDE7B in the asthmatic mice model of ovalbumin-induced airway inflammation and hyper-reactivity." (PMID 30696075, 2019).
PDE7A also shares sentences with these, for which no sentence is quoted: neurological diseases (5 papers); Parkinson disease (4); Alzheimer disease (3); multiple sclerosis (3); neurodegenerative disease (3); respiratory diseases (3); Anxiety (2); chronic lymphocytic leukemia (2); Stroke (2); allergic asthma (1); arteriopathy (1); atherosclerosis (1); autoimmune disease (1); autoimmune hepatitis (1); brain disorder (1); central nervous system diseases (1); chronic obstructive pulmonary disease (1); Cognitive impairment (1); demyelinating disease (1); encephalomyelitis (1); experimental autoimmune encephalomyelitis (1); heart failure (1); Hypercalcemia (1); infarction (1); invasive carcinoma (1); ischemic stroke (1); lung fibrosis (1); mastitis (1); melanoma (1); memory impairment (1).
A further 10 diseases each share a sentence with PDE7A in 1 paper.